BMP4 (bone morphogenetic protein 4)
Diseases named in the same sentence as BMP4 in open-access papers (continued):
Sharing a sentence is not in itself a finding about the gene and the disease.
tumor (continued). "Both the downregulation of SMOC2 stemness gene and the upregulation of enterocytic differentiation genes indicated that tumor organoids were sensitive to BMP4 action (BMP4 and B + D media), while DBZ treatment failed to induce any mucosecretory gene." (PMID 38684650, 2024). "This enhanced tumor growth persisted when low levels of SMAD4 expression were enforced, however, in the presence of BMP4, the time required for 468-GIL tumors expressing SMAD4 to reach 400 mm3 was notably longer (60 days) compared to that for the SMAD4-null tumors (40 days)." (PMID 38689334, 2024). "In the absence of SMAD4, BMP4 promotes primary tumor growth that is accompanied by increased expression of genes associated with DNA replication, cell cycle, and MYC signalling pathways." (PMID 38689334, 2024). "Thus, to promote tumor-induced bone formation, the TRAMP-C2 cell line that expressed BMP4 (TRAMP-BMP4) was generated." (PMID 39061241, 2024). "Despite increased primary tumor growth, BMP4 suppresses metastasis in the absence of tumor cell expression of SMAD4." (PMID 38689334, 2024). "Similar to the observations from BMP4-expressing tumours, lovastatin treatment did not alter the growth of primary tumours." (PMID 39273106, 2024). "To address this, we next investigated the mechanisms by which non-canonical BMP4 signalling promotes tumor growth." (PMID 38689334, 2024). "Following enforced expression of BMP4 in these cells, metastasis to these organs is profoundly inhibited, whilst primary tumour growth is not altered." (PMID 39273106, 2024). "BMP4 expression is required for suppression of metastasis regardless of the SMAD4 status of the tumor cells." (PMID 38689334, 2024). "Deletion of SMAD4 from tumor cells does not prevent BMP4 from suppressing metastasis via a paracrine mechanism." (PMID 38689334, 2024). "For example, MSCs with positive expression of bone morphogenetic protein 4 (BMP-4) and phosphatidylinositol 3,4,5-triphosphate-3-phosphatase (PTEN) also effectively inhibited tumour growth, induced cell cytotoxicity, and significantly prolonged survival in mouse models of various human cancers." (PMID 39120301, 2024). "Contrarily, all tumor organoids analyzed, that harbor a constitutively activated canonical WNT pathway, are mostly unresponsive in terms of cell differentiation to the combined treatment with BMP4 and DBZ." (PMID 38684650, 2024). "In this study, we demonstrated that high glucose induced IR could activate the expression of BMP4 in CRC cells and the tumor of CRC patients with DM." (PMID 37370018, 2023). "The expression of BMP4 and SLC2A1 were acquired by analyzing the TCGA-LIHC dataset, as well as by immunohistochemical analysis of the 40 pairs of human HCC samples and para-tumor tissues." (PMID 37443106, 2023). "To further investigate whether inhibition of BMP4 and BMP2/4 in SMAD4(-) ISO76A cells could attenuate tumor growth and potentiate the effect of cisplatin in the PDX model, we compared the effects of C8C8 and C4C4 with and without cisplatin treatment in vivo." (PMID 35902550, 2022). "Likewise, the high BMP4 limits tumor clonogenicity and the influence of WWOX and AP-2 factors on BMP4 expression is similar to that of KIF7." (PMID 35563688, 2022). "Mechanistically it was shown that the upregulation of CHRDL1 expression results in the counteraction of the tumour-suppressive effects of BMP4 and that the depletion of CHRDL1 significantly reduces cell proliferation and sphere formation as well as tumour growth in a xenograft model." (PMID 36497175, 2022).
tumor (continued). "Consistent with the observed increase in WNT related genes in tumor cells, we saw high scores for WNT-related interactions (ligands Sfrp1 and Wnt5a and receptors Fzd6, Fzd7 and Lrp6) and significant BMP-related interactions (e.g. from Bmp4 with Bmpr1a)." (PMID 35600339, 2022). "We found that BMP2, BMP4 and SHH were highly expressed in tumor, lung and colon." (PMID 35902550, 2022). "Previous findings suggested that BMP4 could upregulate THBS1 expression and BMP4/THBS1 loop suppress tumor angiogenesis." (PMID 36145624, 2022). "Mechanistically the authors proposed that by the epigenetic upregulation of the tumour suppressor CXXC5, the BMP4-response could be mediated." (PMID 36497175, 2022). "A number of studies confirm anti-tumor functions of TSP-1 and BMP-4." (PMID 34501309, 2021). "Gremlin-1 transcripts are found in various different tumor types and can functionally interfere with the TGF-β (transforming growth factor-beta) signaling pathway by the inhibition of the bone morphogenetic proteins BMP2 and BMP4." (PMID 34072967, 2021). "Moreover, BMP4 has been documented to promote the initiation of NSCLC and is highly expressed in NSCLC tumor tissues." (PMID 33472665, 2021). "In addition, IHC staining revealed that TGF-β1, BMP4, ICAM1, and VCAM1 expression was decreased in the ARNTL2-knockdown xenograft tumor tissues." (PMID 32826856, 2020). "In addition, after tumor organoids were cultured in the presence of the Bmp4 protein to increase the BMP response, the Bmp4-treated organoids grew slowly, and the efficiency of organoid formation was significantly reduced." (PMID 31036156, 2019). "Tumor cells were treated with TNF in combination with TGF-β-type proteins and BMP4." (PMID 28423685, 2017). "This demonstrated that cancer cell lines with a molecularly defined EMT phenotype are responsive to BMP4‐induced cell migration, irrespective of tumour subtype gene signature." (PMID 28299802, 2017). "Our initial analysis suggested that non-CNS tumor growth led to demethylation of BMP4 promoter in the PFC tissues of tumor-bearing animals as compared to intact ones." (PMID 28758896, 2017). "Similarly, another SMO inhibitor, LDE-225, and a BMP4 blocking antibody were used in the co-culture system (with SKOV3 and CAOV-3 tumor cells) and both demonstrated a reduction in CA-MSC derived BMP4 and tumor derived HH." (PMID 26755648, 2016). "Next, we examined by qRT-PCR if FOXC2 knockdown in U2OS cells affects the expression of several genes known to be enriched in tumor-propagating cells, such as the cell surface marker CD133, multidrug resistance pump ABCG2, Notch signaling receptor ligands JAG1 and BMP4, and chemokine receptor CXCR4." (PMID 27634875, 2016). "Similarly, bone morphogenetic proteins (BMPs)— BMP2, BMP4, and BMP7, and all-trans RA have been shown to inhibit tumor initiation by promoting astorglial and neuronal differentiation in GBM cells." (PMID 26307681, 2015). "We treated our cells with an increasing concentration of BMP4 and observed decreased proliferation in control tumor cells yet no significant change in our cKO cells by thymidine incorporation." (PMID 26274893, 2015). "Therefore, in order to determine the effect of ECCM on differentiated tumor cells, we forced in vitro differentiation of GBM CSCs toward the neuronal and astrocytic lineages using bone morphogenetic protein 4 (BMP4)." (PMID 26282129, 2015). "Among all BMP ligands tested, BMP4 elicited the strongest effect, which could effectively inhibit not only GIC proliferation and self-renewal in vitro, but also tumor growth in vivo." (PMID 26487967, 2015). "Similarly, transient exposure of GSCs to bone morphogenetic protein 4 (BMP4), a well-known differentiation factor, abolishes the tumor initiating and infiltrating potential." (PMID 25992628, 2015). "Nevertheless they observed that BMP4 did have a favorable effect on GBM: it reduced tumor size and tumor invasion although there was no synergistic effect with bevacizumab treatment." (PMID 24877113, 2014).
tumor (continued). "When mice with a higher tumor burden were injected with the VACV lacking BMP-4, 80% of the mice showed tumor recurrence." (PMID 23800258, 2013). "BMP4 produced by HCC cells has an autocrine effect promoting invasion and anchorage independent growth, together with a paracrine effect increasing tube formation in endothelial cells, thus promoting tumor vasculogenesis." (PMID 23936038, 2013). "BMP4 stimulated fibroblasts significantly increased the number of tumor cells invaded through BD Matrigel, while inhibition of BMP signaling via DMH1 treatment statistically significantly reduced the number of invaded tumor cells." (PMID 23840733, 2013). "In order to test the activity of the BMP-4 VACV in the GBM CSC FLuc animal model, GLV-1h285 and GLV-1h189 were injected at the same coordinates as the tumor cells two weeks after implantation in a low tumor burden setting." (PMID 23800258, 2013). "Furthermore, BMP4 and BMP6 are overexpressed in both human HCC cell lines and tissues and importantly, BMP4 expression strongly correlates with high tumor grade having recently being proposed as marker for the prediction of HCC recurrence and prognosis." (PMID 23936038, 2013). "In the GBM CSC animal models we observed a benefit in treating the tumor with the BMP-4 virus without any overt side effects in two different tumor burden settings." (PMID 23800258, 2013). "Preliminary studies in glioblastoma demonstrate that BMP2, BMP4 and BMP7 treatment inhibits sphere forming and induces differentiation of CD133+ cells; moreover CD133+ cells pre-treatment with these cytokines attenuates tumor formation in mice." (PMID 24212789, 2011). "This BMP4-induced premature senescence is mediated through Smadsignaling to up-regulate p16INK4a and p21WAF1/ cip1.BMP4 and other BMP signaling pathways were also found to participate insenescence of multiple cancer cell types or in the inhibition of tumor cellgrowth." (PMID 20157553, 2009). "Additionally, Bone Morphogenetic Protein 4 (BMP4) directly binds to the PKM promoter via SMAD5, upregulating PKM2 expression and enhancing glycolytic flux, thereby promoting glucose metabolism reprogramming and tumor progression." (PMID 41169372, 2025). "While we do not claim to capture the full complexity of a GBM tumor, we believe that our model captures the key non-linear dynamics that are critical for characterizing the effects of any potential differentiation therapy such as BMP4." (PMID 41279885, 2025). "Bone morphogenetic protein 4 (BMP4), a growth factor with anti-proliferative properties, has been proposed as a therapeutic option for GBM since it downregulates stemness markers like SOX2, inhibits tumor growth, and induces (reversible) astrocytic differentiation." (PMID 40362216, 2025). "BMP4 can also signal through a non-canonical pathway, particularly in cells with loss of SMAD4, a common tumour suppressor gene, resulting in the activation of PI3K/AKT, NF-κB and MAPK pathways capable of promoting tumour progression." (PMID 39273106, 2024). "The benefit of statin use was most evident in patients whose tumours expressed low levels of BMP4, with a non-significant trend towards benefit in patients with high-BMP4 tumours (HRs for distant relapse-free survival, 0.25 and p = 0.019; 0.40 and p = 0.13, respectively)." (PMID 39273106, 2024). "Importantly, the expression of BMP4 did not affect the growth of primary tumours and the RNA sequencing data were generated from MDA-MB-231HM cells resected at the same time point." (PMID 39273106, 2024). "We re-analysed the transcriptomic data from tumour cells recovered from orthotopic primary breast MDA-MB-231HM tumours in immunocompromised mice with or without enforced expression of BMP4 and we also completed a proteomic analysis of tumour cell responses to BMP4 exposure." (PMID 39273106, 2024).
tumor (continued). "We hypothesized that the activity of SMAD4 mediates the anti-metastatic activity of BMP4, and that when SMAD4 is lost, non-canonical BMP4 signalling promotes tumor growth and metastasis." (PMID 38689334, 2024). "As with all therapies that have been described for GBM patients, improved tumor stratification is, in any case, necessary to reach the appropriate responsive patient subcategory especially since (albeit in a small subset of tested patients) TMZ + BMP4 sometimes has an antagonistic effect." (PMID 39337661, 2024). "The tumor promoting effect of BMP4 is potentially mediated by SMAD4-independent non-canonical signalling that leads to accelerated DNA replication and cell cycle progression, which needs to be considered if patients with SMAD4-low/null tumors were to receive therapies that activate BMP signalling." (PMID 38689334, 2024). "Therefore, the changes observed in BMP4-expressing tumours were not driven by factors such as the rate of tumour growth." (PMID 39273106, 2024). "Importantly, although we found a reduction of tumor size by BMP4 gene therapy, it did not promote bone formation." (PMID 31956851, 2020). "Importantly, a genome-wide gene expression profile established during hepatitis B virus-induced HCC model pointed to BMP7 and BMP4 as candidates for common regulators of genes involved in the non-tumour to tumour-transition." (PMID 29295498, 2017). "However, experimental studies using tumor cells have demonstrated that CR-1 is closely regulated by transforming growth factor (TGF)-β superfamily members, and particularly by TGF-β1 and bone morphogenetic protein (BMP)-4, both expressed by endometrial cells." (PMID 25165718, 2014). "Thus BMP4 is required for suppression of metastasis regardless of tumor SMAD4 status." (PMID 38689334, 2024). "Likewise, recent findings demonstrated that BMP4 overexpression in LCs amplifies the generation of M2-like macrophages with protumor characteristics, evidenced by a decreased TNFα/IL-10 expression ratio and increased levels of CCL2 and IL-6, promoting tumor progression." (PMID 38299154, 2023). "Tumours derived from the triple-negative MDA-MB-231HM line, with or without exogenous BMP4 expression, were recovered and subjected to RNA sequencing in our previous study." (PMID 39273106, 2024). "In contrast, BMP4 accelerated the growth of tumors with reduced SMAD4 expression, implicating a tumor growth-promoting role of non-canonical signalling." (PMID 38689334, 2024). "In BMP4-expressing 231-HM tumors that lacked tumor-intrinsic SMAD4 expression, SMAD4 was still present in stromal cells, and canonical BMP4 signalling in the stroma was still likely to be functional." (PMID 38689334, 2024). "We assessed the requirement for tumor cell expression of SMAD4 in mediating responses to BMP4, demonstrating that BMP4 is required for suppression of metastasis, regardless of the SMAD4 status of the tumor cells." (PMID 38689334, 2024). "To distinguish the consequences of SMAD4-dependent (canonical) and SMAD4-independent (non-canonical) signalling, we generated several tumor lines with modified levels of SMAD4 and/or BMP4." (PMID 38689334, 2024). "Then we compared the expression of each member in ccRCC tissues and corresponding noncancerous normal tissues, unfortunately we found that BMP4, BMP5, and BMP7 expression was lower in tumor tissues." (PMID 31155610, 2020). "Both BMP4 and CST6 are metastasis suppression genes downregulated in 231_HM.LNm5 tumour cells relative to non-metastatic 231_ATCC tumour cells, and both contain CpG islands spanning their transcription start sites in their 5′ proximal regions." (PMID 29720474, 2018). "In agreement with our previous reports but contradicting a report by another group where a trend towards accelerated experimental metastasis in BMP4-treated mice was observed, in 231-HM and 4T1.2 tumors that expressed SMAD4, enforced BMP4 expression did not alter tumor growth kinetics." (PMID 38689334, 2024).
tumor (continued). "Moreover, only IL-10 and BMP4 show modest enhancement of HHLA2 expression in monocytes and dendritic cells, but not in ccRCC tumor cells." (PMID 37891555, 2023). "To further prove that the observed tumor phenotype is BMP signaling dependent, not due to the nonspecific positional effort of transgene integration, we generated Nse-BMP4;Nse-Noggin double transgenic mice by mating Nse-BMP4 with Nse-Noggin mice." (PMID 22168923, 2011). "Furthermore, to reveal mechanisms by which BMP4 regulates tumor progression in the presence and absence of SMAD4, we have completed transcriptomic analyses of the canonical and non-canonical signalling pathways that are modulated by BMP4." (PMID 38689334, 2024). "However, we did not see a tumor rebound in the BMP-4 virus treated group, supporting the hypothesis that BMP-4 production could disrupt cancer stem cell propagation in GBM." (PMID 23800258, 2013).